PIK3CA (phosphatidylinositol-4,5-bisphosphate 3-kinase catalytic subunit alpha)
Diseases named in the same sentence as PIK3CA in open-access papers (continued):
Sharing a sentence is not in itself a finding about the gene and the disease.
ovarian tumors (18 papers, 2009 to 2024). "Our analysis revealed a pan‐cancer prevalence of PIK3CA mutations in 13.0% of the samples, with the highest occurrence observed in uterine/endometrial, breast, cervical, and ovarian tumors." (PMID 39054873, 2024). "The diagnosis of the ovarian mucinous cystadenoma was prompted by the detection of a PIK3CA variant, an alteration present in about 12% of ovarian tumors across various histological types." (PMID 39512764, 2024). "Further, an oncogenic PIK3CA mutation coupled with PTEN loss was shown to initiate ovarian tumors in mice." (PMID 31289610, 2019). "In contrast, the somatic mutations in CTNNB1 and PIK3CA were detected not only in the endometrial and ovarian tumours, but also in the lung metastasis." (PMID 28103826, 2017). "In addition, PIK3CA mutation is rare in borderline or early-stage ovarian tumors (our unpublished observation)." (PMID 19172191, 2009). "In addition, the ER is highly expressed in subsets of ovarian tumors with PIK3CA mutations." (PMID 35735430, 2022). "Gain of function (GoF) mutations were identified in PIK3CA and TBX3 in one breast and one ovarian tumor, respectively." (PMID 36344544, 2022). "PIK3CA and ARID1A mutations were more frequent in clear cell or endometrioid tumors than in other types (6/7 vs. 4/15 and 4/7 vs. 3/15; P = 0.016 and 0.11, respectively), consistent with previous studies of all-age-group ovarian tumors." (PMID 29464067, 2018). "Then, we followed up the ovarian tumor development in PIK3CA-Tg mice." (PMID 19172191, 2009). "Our study showed a lower incidence of PIK3CA mutations (3.9%), indicating that the PIK3CA gene mutation is not a common mechanism in the activation of PIK3CA in Middle Eastern ovarian tumors." (PMID 19638206, 2009). "Our data showed mutual exclusivity between the molecular event of PIK3CA amplification and mutations in PIK3CA, KRAS, BRAF genes, which suggests that each of these alterations may individually be sufficient to drive ovarian tumor pathogenesis independently." (PMID 19638206, 2009). "Interestingly, ARID1A mutations frequently co-occur with PIK3CA or PTEN mutations in human tumors, and double mutations of Arid1a with Pten or Pik3ca result in ovarian tumor formation in mice suggesting a cooperative carcinogenic role of PI3K and chromatin remodeling pathways." (PMID 31481116, 2019). "Likewise, genes frequently amplified (MYC, PIK3CA and AURKA) or lost (RB1, PTEN) in ovarian tumours were also commonly multiplied or lost in our set of patient cells." (PMID 29180611, 2017). "In an animal model, mice with both ARID1A homozygous deletion and H104R activating mutation of PIK3CA in ovarian surface epithelium rapidly developed ovarian tumours with haemorrhagic ascites and peritoneal metastases, whereas those with ARID1A deletion or PIK3CA mutations alone did not." (PMID 38275587, 2023).
sarcoma (18 papers, 2011 to 2025). A usually aggressive malignant neoplasm of the soft tissue or bone. "The only significant exception to this rule was the PIK3CA gene, whose mutations appeared to be associated with sarcomas of different types and in various topographies." (PMID 37568749, 2023). "The only significant exception to this rule seems to be the PIK3CA gene, whose mutations seem to be associated with sarcomas of different topographies and types, suggesting a crucial role for PIK3CA in different sarcomas." (PMID 37568749, 2023). "The utility of buparlisib as an effective therapeutic agent is also influenced by the prevalence of activating PIK3CA mutations in sarcoma since increased single agent sensitivity is observed for tumors harboring these mutations." (PMID 26402468, 2015). "These tumors may be associated with microsatellite instability and mutations in phosphatase and tensin homolog, phosphatidylinositol-4,5-bisphosphate 3-kinase catalytic subunit alpha, Kirsten rat sarcoma and Catenin Beta 1 (PTEN, PIK3CA, K-ras and CTNNBI)." (PMID 33912318, 2021). "Although further studies are needed to validate this, this observation suggests an important role for the PIK3CA gene across different sarcoma subtypes." (PMID 37568749, 2023). "Three patient tumor samples had both a PIK3CA mutation and PTEN loss by IHC (myxoid liposarcoma, rhabdomyosarcoma and sarcoma, NOS)." (PMID 25906748, 2015). "Among disease entities with more than 10 patients tested, no PIK3CA mutations were found in sarcomas, and adenocarcinomas of stomach and esophagus." (PMID 21829508, 2011). "Analyses revealed that the tumors not only harbored mutations characteristic of sarcoma, such as RB1 (50%), ATRX (38%), and FBXW7 (17%) mutations, but also possessed mutations commonly associated with endometrial adenocarcinoma, including PTEN (42%), PIK3CA (42%), and AKT (17%) mutations." (PMID 41181577, 2025). "In this subtype of sarcoma, CDKN2A firmly connects to MDM2, CCND1, PIK3CA, CDK4, CBX7, and less firmly to EGFR, and IL-6." (PMID 34359782, 2021). "Advancements in genetic and molecular profiling allowed several abnormalities located in the phosphatidylinositol-4,5-bisphosphate 3 kinase catalytic subunit alpha (PIK3CA) and neuroblastoma RAS viral oncogene homolog (NRAS) pathways to be identified in canine sarcomas." (PMID 39195816, 2024). "Additionally, these models frequently develop sarcomas rather than adenocarcinomas, the latter of which are the most common PIK3CA-mutant tumor type in patients." (PMID 39808497, 2025). "However, because of its rarity of sarcoma, no exact frequency of PIK3CA amplification has been identified in sarcoma." (PMID 27016421, 2016).
gastric adenocarcinoma (16 papers, 2005 to 2024). "AZD5363 in combination with paclitaxel has been utilized in a phase II clinical trial in patients with PIK3CA mutation and PIK3CA amplification in advanced gastric adenocarcinoma." (PMID 35392233, 2022). "Variants in PIK3CA are found in 15% of the stomach adenocarcinomas (5 studies; 739 samples) and 18% of these cancers harbor the p.(His1047Arg) missense variant." (PMID 34075207, 2021). "Analysis in stomach adenocarcinoma identified EBV-positive cases involving PIK3CA mutations and/or CDKN2A silencing with biologically more determination, compared to previous reports." (PMID 30837539, 2019). "In a comprehensive molecular characterization of 295 primary gastric adenocarcinomas as part of the TCGA project a high mutation frequency in PIK3CA (42%) in MSI tumors was reported." (PMID 28683819, 2017). "Using high throughput mutation screening platform, we identified that PIK3CA mutations were the most frequently observed target for gastric adenocarcinoma." (PMID 22723903, 2012). "Large-scale screening of gastric adenocarcinomas for PIK3CA mutations revealed a mutation incidence of 4.3%." (PMID 15784156, 2005). "Among the 94 gastric adenocarcinoma analysed, we have detected PIK3CA mutation in 4 cases." (PMID 15784156, 2005). "In this study, we have examined a series of 94 human gastric adenocarcinomas for PIK3CA mutation." (PMID 15784156, 2005). "We demonstrate that co-activation of the KRAS and PIK3CA/PTEN signaling pathways is sufficient for the development of early-stage gastric adenocarcinomas." (PMID 39128004, 2024). "For example, a clinical correlation analysis of ctDNA in patients with gastric adenocarcinoma showed that PIK3CA is one of the most frequently affected character-altered alterations, which can help to indicate clinically relevant genomic data for clinical diagnosis and treatment." (PMID 33693004, 2021). "We also observed frequent PIK3CA mutations, associated with the EBV+ subtype, in gastric adenocarcinoma and EA, with a decrease in CCNE1-amplified versus nonamplified gastric adenocarcinoma (1.9% vs. 9.2%, P = 0.01) and a similar frequency in CCNE1-amplified versus nonamplified EA." (PMID 38717153, 2024).
oral cancer (16 papers, 2016 to 2025). "As described by Shigeishi (2023), in HPV-positive oral cancers, mutations in the PIK3CA gene are frequently observed, while there are somatic mutations in ZNF750, FGFR3, DDX3X, CASZ1, PTEN, and CYLD, differentiating them from HPV-negative oral cancers." (PMID 40284955, 2025). "Most common mutational sites are in exon 9 and exon 20 of PIK3CA in oral cancer." (PMID 35047986, 2020). "In existing oral cancer studies, an increase in the frequency of PIK3CA gene amplification has been reported in 16.70% to 100% of patients." (PMID 33287350, 2020). "Some of these genes, including AKT, BRAF, PIK3CA, NRAS, GSK3, CNND1, etc., are involved not only in oral cancers but, generally, in several solid tumors." (PMID 31052345, 2019).
papillary thyroid carcinoma (16 papers, 2006 to 2026). "In an initial study, PIK3CA mutations were identified in the highest proportion in the anaplastic thyroid carcinomas (16%), followed by follicular thyroid carcinomas (8%), and papillary thyroid carcinomas (2%)." (PMID 31905960, 2019). "c-Met, the hepatocyte growth factor receptor, was associated with p-Akt expression in papillary thyroid carcinomas in a Middle Eastern population in which PIK3CA mutation was rare." (PMID 26793165, 2015). "In thyroid papillary carcinoma, somatic mutations in PIK3CA and AKT1 are found in limited cases." (PMID 38501028, 2024). "The literature proposes that the occurrence of PIK3CA mutations may be less useful than TERT promoter mutations for assessing the risk of anaplastic transformation in papillary carcinoma." (PMID 36672362, 2023). "For instance, a higher incidence of PIK3CA alterations was found in Middle Eastern papillary thyroid cancer patients." (PMID 36212501, 2022). "MiR-363-3p can also function as a tumor suppressor in papillary thyroid carcinoma, where its suppressive effect is mediated by repression of PIK3CA." (PMID 33744854, 2021). "We report PIK3CA E545K MF measurements in those tissues, as well as in normal breast, normal thyroid, mammary ductal carcinomas, and papillary thyroid carcinomas." (PMID 28755461, 2017). "A number of gene alterations, such as point mutations in RAS and BRAF genes, point mutations or amplification of PIK3CA, and fusion genes involving RET, NTRK1 and PPARγ are known to frequently occur in differentiated thyroid carcinoma, and are correlated to different morphological subtypes." (PMID 22087789, 2011). "The aim of our study was to examine a gene expression level of PIK3CA in fine-needle aspiration biopsy (FNAB) thyroid specimens in two types of thyroid lesions, papillary thyroid carcinoma (PTC) and non-toxic goitre (NTG)." (PMID 20804548, 2010).
brain tumors (15 papers, 2007 to 2025). "This is consistent with studies of PIK3CA variants in brain tumors and mouse models with patient-related Pik3r2 mutations, which are less common causes of intractable epilepsy." (PMID 34899181, 2021). "A large-scale mutational analysis of the helical and catalytic domains of PIK3CA was performed in brain tumors." (PMID 19384426, 2007). "Pik3ca NS mutations were detected in 13/14 (93%) brain tumors and 7/9 (78%) heart tumors." (PMID 38232086, 2024). "Mutations in the PIK3CA gene are relevant in the PI3K/AKT signaling pathway, which is involved in tumors of the brain, colorectal, breast, and other tumor types, and is associated with cell proliferation, invasion, and metastasis." (PMID 34202354, 2021). "Subsequently, PIK3CA inhibitors may warrant investigation for the treatment of these brain tumors." (PMID 37524847, 2023).
lymphoma (15 papers, 2010 to 2024). A malignant (clonal) proliferation of B- lymphocytes or T- lymphocytes which involves the lymph nodes, bone marrow and/or extranodal sites. "Traditionally, PTEN and PIK3CA mutations have been thought to be mutually exclusive, when studied in lymphomas, breast and brain cancers." (PMID 37465112, 2023). "A phase II study on taselisib is ongoing for patients with PIK3CA mutation and advanced refractory solid tumors, lymphomas or MM (NCT02465060)." (PMID 36523963, 2022). "PI3K expression is frequently constitutively active in lymphomas as a result of gene amplification or duplication of wild type PIK3CA, which encodes a subunit of PI3K, wherein inhibition of PIK3CA activity results in cell apoptosis." (PMID 32284791, 2020). "Previous study had declared that blocking PIK3CA can significantly induce lymphoma cell cycle arrest and then induce apoptosis by completely eliminating p-Akt and its downstream target." (PMID 33985517, 2021). "In lymphomas, PIK3CA has been reported to be amplified in 15/22 (68%) cases of mantle cell lymphoma (MCL), 9/161 (5.6%) cases of chronic lymphocytic leukemia (CLL), and mutated in 1/76 (1.3%) cases of DLBCL; while PIK3CD has been reported to be mutated in 3/73 (4.1%) cases of DLBCL." (PMID 24418330, 2014). "As an example of entity-dependent mutations, alterations in the PI3K/AKT/MAPK signaling pathway, in particular in PIK3CA, are detected in EBV-associated NPC and GC but not in EBV-associated lymphoma." (PMID 34680337, 2021).
cervical adenocarcinoma (14 papers, 2014 to 2026). An adenocarcinoma arising from the cervical epithelium. "Several recurrent alterations identified in this cohort, including activating mutations in PIK3CA and cervical adenocarcinoma, comprise several histological subtypes with distinct etiologies and clinical behaviors." (PMID 41597409, 2026). "PIK3CA mutations are associated with decreased progression-free and overall survival of cervical adenocarcinoma patients." (PMID 40647429, 2025). "The most significant finding in the study was that the measurement of three single-point nonsynonymous mutations in PIK3CA: E542K, E545K, and H1047R using ddPCR is predictive of survival in a subgroup of cervical adenocarcinoma." (PMID 34203201, 2021). "In a prior retrospective study, we identified mutations in FAT1, ARID1A, ERBB2, and PIK3CA in whole-exome sequencing of 15 patients with cervical adenocarcinoma." (PMID 34203201, 2021). "In our study, PIK3CA appeared to be a frequently altered gene in cervical adenocarcinoma, with missense mutations in 4 of 20 (20%) tumors, consistent with previous reports (8–37.5%)." (PMID 33398034, 2021). "The discrepancy of the PIK3CA mutation detection rate in tumor tissue of cervical adenocarcinoma among these reports were attributed to the differing purity of tumor cells in a sample, differing sensitivity of the measurement, or differing populations and regions as well as differing sample sizes." (PMID 34203201, 2021). "It is the first indication of the predictive power of PIK3CA mutations in cervical adenocarcinoma." (PMID 34203201, 2021). "Fourth, in our study, after the evaluation of WES data in 20 cervical adenocarcinomas, six genes (i.e., PIK3CA, KRAS, TRAPPC12, NDN, GOLGA6L4, and BAIAP3) were predicted as driver genes that could promote tumor formation and development." (PMID 33398034, 2021). "It is the first indication of the predictive power of PIK3CA aberration in cervical adenocarcinoma." (PMID 34203201, 2021). "The stratification of patients with cervical adenocarcinoma, regardless of stage, based on the PIK3CA mutation could be implemented in a clinical setting able to perform ddPCR assays on liquid biopsies, and may offer the possibility of tailoring management." (PMID 34203201, 2021). "We identified PIK3CA, NDN, GOLGA6L4, and BAIAP3 as SMGs in cervical adenocarcinoma and confirmed that NDN, GOLGA6L4, and BAIAP3 were novel SMGs." (PMID 33398034, 2021). "Except for PIK3CA and KRAS, the four other genes were identified as novel driver genes in cervical adenocarcinoma, which might need further validation." (PMID 33398034, 2021). "Common genetic aberrations found in endometrial and other types of cervical adenocarcinoma, such as PTEN and PIK3CA, are not reported in MNAC." (PMID 31266530, 2019).
colorectal adenocarcinoma (14 papers, 2011 to 2025). The most common type of colorectal carcinoma. "We observed that 10~30% of colorectal adenocarcinomas are associated with PIK3CA mutations, while 20~50% of patients are associated with a KRAS mutation status." (PMID 36652260, 2023). "The PBF-fixed samples of the 25 colorectal adenocarcinomas collected in the study had been routinely subjected to Sequenom MassARRAY® to screen for KRAS/NRAS/BRAF/PIK3CA mutations." (PMID 28796828, 2017). "PIK3CA, the gene encoding for the catalytic alpha sub-unit of kinase PI3K is often mutated in prevalent cancers such as breast cancer and colorectal adenocarcinomas." (PMID 36295658, 2022). "In one study of colorectal adenocarcinoma, the frequency of different mutations (KRAS, BRAF, NRAS, and PIK3CA) were found to vary significantly with the location of the metastasis (lung, brain, and liver)." (PMID 23119210, 2012).